HIF1A (hypoxia inducible factor 1 subunit alpha)
Diseases named in the same sentence as HIF1A in open-access papers (continued):
Sharing a sentence is not in itself a finding about the gene and the disease.
pancreatic cancer (continued). "Tumour hypoxia, a feature typical for pancreatic cancer may further increase the angiogenic effect of MSC, as our in vitro data show the expression of HIF-1α by pancreatic cancer cells under hypoxic conditions, which, in turn, leads to expression and secretion of VEGF by tumour cells." (PMID 18665180, 2008). "In pancreatic cancer, CAFs—a major source of TGF-β1—secrete ECM proteins that further activate HIF-1α, establishing a “hypoxia-TGF-β1-ECM” positive feedback loop." (PMID 40406267, 2025). "In this study, we investigated the interplay between HIF-1α and TGF-β1 in regulating ECM protein expression through the Smad signaling pathway in pancreatic cancer." (PMID 40406267, 2025). "Our study found that HIF-1α and TGF-β1 are significantly overexpressed in pancreatic cancer tissues and collaboratively drive ECM protein synthesis via the Smad signaling pathway." (PMID 40406267, 2025). "Immunohistochemistry showed that the HIF-1α/MMP2 and HIF-1α/MMP9 signaling pathways in the tumor model were blocked, proving the role of the HIF-1α/MMPs signaling pathway in the occurrence and development of pancreatic cancer." (PMID 40563539, 2025). "Clinical specimens showed significantly elevated expression of both HIF-1α and TGF-β1 in pancreatic cancer tissues compared to adjacent normal tissues, correlating with advanced disease stages." (PMID 40406267, 2025). "Our study reveals that HIF-1α and TGF-β1 cooperatively regulate pancreatic cancer ECM remodeling through direct interaction and Smad signaling, providing a foundation for therapeutic strategies targeting this axis." (PMID 40406267, 2025). "This study investigated the relationship between hypoxia-inducible factor-1α (HIF-1α) and transforming growth factor-β1 (TGF-β1) in regulating ECM protein expression in pancreatic cancer." (PMID 40406267, 2025). "Immunohistochemical analysis revealed distinct expression patterns of HIF-1α and TGF-β1 in pancreatic cancer tissues compared to adjacent normal tissues." (PMID 40406267, 2025). "P4HA1 in turn enhanced HIF1α stability, indicating a positive feedback loop between HIF1α and P4HA1 in pancreatic cancer." (PMID 39966387, 2025). "The mechanism is that salidroside inhibits the expression of HIF-1α, MMP2, and MMP9 in BxPC-3 cells, making it a potential adjuvant drug for the treatment of pancreatic cancer." (PMID 40563539, 2025). "In pancreatic cancer cell lines, MIF stabilizes the structure of HIF-1α through CSN5, which in turn further up-regulates the expression of MIF." (PMID 41210694, 2025). "Recent reports show that histone deacetylase 4 (HDAC4) regulates HIF-1α protein acetylation and stability and ALKBH5 regulates m6A-modification of HDAC4 transcripts under hypoxic conditions in pancreatic cancer cells." (PMID 38227578, 2024). "Subsequently, YAP forms a complex with hypoxia inducible factor 1 subunit alpha (HIF1A) in the nucleus, further activating dedifferentiation of CD133-negative pancreatic cancer cells." (PMID 38725632, 2024). "Pancreatic cancer has a highly hypoxic microenvironment in which HIF-1α is activated, and it subsequently activates the MET in pancreatic cancer, promoting stromal–tumor communication and inducing neo-angiogenesis." (PMID 38473413, 2024). "TAM is one of the most well-known regulators of hypoxia-inducible factor 1 alpha (HIF-1α) as it is reported to reduce the levels of HIF-1α and estrogen receptor alpha (ER-α) in many cancer cells including BC and pancreatic cancer." (PMID 39167288, 2024). "To validate the results from the pharmacological inhibition of HIF-1α, we generated a genetic knockout of HIF-1α-coding gene (HIF1A) in S2-013 and HPAF-II pancreatic cancer cells by utilizing CRISPR/Cas9 technology." (PMID 38547055, 2024). "It reduces the phospforylation of focal adhesion kinase (FAK), hypoxia-inducible factor 1—alpha (HIF1A factor), and the synthesis of vascular endothelial growth factor (VEGF) in colon, ovary, and pancreatic cancer." (PMID 38542201, 2024).
pancreatic cancer (continued). "circ_0000977 was shown to sequester miR-153 and relieve the repression of HIF1α and ADAM10 mRNA in pancreatic cancer cell line Panc-1." (PMID 39403602, 2024). "In pancreatic cancer cells, UHRF1 overexpression promotes aerobic glycolysis and supports tumor growth and metastasis, in part by stabilizing HIF1α and enhancing the transcription of glycolytic genes." (PMID 39682281, 2024). "It downregulates the levels of HIF-1α, GLUT-1, and VEGF in pancreatic carcinoma and inhibits the level of MMP-2, MMP-9, uPA, and VEGF in TRAMP mouse by downregulating IGF-I/IGFBP-3 signaling." (PMID 38611849, 2024). "In pancreatic cancer, IGF-IR, STAT3, HIF-1α, IL-6, IGF-1, amongst others, have been described to be active and linked to the HSP90 pathways." (PMID 36966394, 2023). "In pancreatic cancer, hypoxic exosomal circZNF91/miR-23b-3p/SIRT1/HIF-1a formed a positive feedback loop that co-regulates gemcitabine resistance in pancreatic cancer cells under hypoxia." (PMID 37213665, 2023). "Kaempferol glycosides induced ubiquitin-proteasome-dependent degradation of HIF1α, which inhibited hypoxia signaling and expression of GLUT1 in pancreatic cancer cells." (PMID 38001865, 2023). "For instance, hypoxic conditions elevate the levels of hypoxia-inducible factor 1-alpha (HIF-1α), which, when present in sufficient quantities, activates HH signaling in pancreatic cancer cells, thereby promoting epithelial–mesenchymal transition and invasion." (PMID 38020914, 2023). "Recent study has demonstrated that HMGB1 triggered both YAP and HIF-1α nuclear translocation and enhanced YAP and HIF-1α interaction promoting pancreatic cancer stemness." (PMID 36594102, 2023). "It has been reported that YEATS2 can act as a target of HIF1α and regulate the TAK1/NF-κB pathway to promote tumor progression in pancreatic cancer." (PMID 36980736, 2023). "We also found that HIF1α knockdown strongly decreased the mRNA and protein levels of ALKBH5 in hypoxic pancreatic cancer cells." (PMID 37149664, 2023). "For example, when DFO and the HIF-1α inhibitor YC1 were formulated into transferrin-decorated liposome nanoparticles and targeted to transferrin receptor-expressing pancreatic cancer xenografts in mice, xenograft tumor regression was observed." (PMID 36980731, 2023). "Our assays also demonstrated that hypoxia-induced HDAC4 enhanced HIF1a protein stability, and overexpressed HIF1a promoted transcription of ALKBH5 in hypoxic pancreatic cancer cells." (PMID 37149664, 2023). "The expression levels of HIF-1α and GM-CSF in PANC-1 pancreatic cancer cells were increased when cultured in the hypoxic condition compared with those in the normoxic condition." (PMID 36551540, 2022). "It has been shown that under hypoxic conditions, NF-κB activates the transcription of HIF-1α and its target gene VEGF-A, resulting in the increased secretion of VEGF, and enhanced angiogenesis in hypoxic pancreatic cancer cells." (PMID 36408139, 2022). "Several other reports have demonstrated miRNA playing a biological role in pancreatic cancer pathways, such as those targeting TXNIP-Mediated HIF1α, E2F5, TGF-β2/TGF-βRIII, HIF1α, and PTEN." (PMID 35740894, 2022). "When shRNA was used to knock out hypoxia-inducible factor-1α in pancreatic cancer cells, STIM1 mRNA and protein were significantly reduced in the pancreatic cancer cells with HIF-1α gene knockout." (PMID 36187789, 2022). "As an important target gene of HIF1α, VEGF also plays important roles in the regulation of glucose metabolism in pancreatic cancer." (PMID 35493517, 2022). "Downregulating the expression of miR-142 increases HIF-1α expression to upregulate EMT-related proteins, eventually enhancing the invasion and migration of pancreatic cancer cells." (PMID 35798726, 2022).
pancreatic cancer (continued). "In pancreatic cancer cells, APG suppresses the expression of HIF-1α and VEGF and induces cell death via the PI3K/Akt/GSK-3 signaling under both normoxia and hypoxia." (PMID 34948250, 2021). "Further, it was connoted that CASC9, a hypoxia-inducible lncRNA, is regulated by HIF-1α and drives glycolysis via the upregulation of hexokinase 2 (HK2), lactate dehydrogenase A (LDHA), and glucose transporter type 4 (GLUT4) levels in pancreatic cancer." (PMID 34298879, 2021). "We developed an anti-HIF-1α nanobody and showed the function of VHH212 in a preclinical murine model of PANC-1 pancreatic cancer." (PMID 33830713, 2021). "circ_0000977 in pancreatic cancer can adsorb miR-153 to affect the expression of HIF1A and ADAM10 as well as regulate the immune escape of pancreatic cancer cells mediated by HIF1A." (PMID 33937077, 2021). "LBH589 (panobinostat), a pan-HDAC inhibitor that indirectly promotes the degradation of HIF-1α, demonstrates antitumor effects in HCC, pancreatic cancer, NSCLC, and glioblastoma." (PMID 33808542, 2021). "To confirm the increased population as TAMs, we sorted the CD11b + F4/80 + cells from the pancreatic tumors using a FACS sorter and quantified the expression of some TAM markers, such as HIF-1α, CCL2, and PECAM1, with qRT-PCR." (PMID 34150748, 2021). "In pancreatic cancer, P4HA1 can promote glycolytic and malignant phenotypes through the P4HA1/HIF1α feedback loop and in ovarian cancer, P4HA1 promotes tumor metastasis by regulating the epithelial-mesenchymal transition (EMT)." (PMID 33952718, 2021). "Herein, we found that salidroside suppressed hypoxia‐inducible factor 1 alpha (HIF‐1α) and lysyl oxidase‐like protein 2 (LOXL2) within human pancreatic cancer BxPC‐3 cells cultured both under normoxia and hypoxia condition." (PMID 31162697, 2020). "Conversely, lncRNA- CF129 indirectly inhibits HIF-1α expression via lncRNA-interacted feedback of HIF-1α and FOXC2, and reduced in pancreatic cancer during hypoxia microenvironment." (PMID 32550915, 2020). "HIF-1α bound to the HRE of MT2-MMP and activated its transcription, overexpressing MT2-MMP clearly mitigated the apoptosis of pancreatic cancer cells." (PMID 32587480, 2020). "Further, c-Myc knockdown decreased the expression of HIF-1α/SDF-1/CXCR4 and enhanced the antitumor effect of bufalin in pancreatic cancer cells." (PMID 32362830, 2020). "The influence of HIF-1α on ZEB1 was also evaluated among bladder cancer, glioblastoma and pancreatic cancer cells." (PMID 32322559, 2020). "P-AscH can also increase extracellular H2O2 and transport it into tumor cells through the plasma membrane to inhibit the expression of HIF-1α and VEGF, exerting a killing effect on pancreatic cancer cells." (PMID 32587480, 2020). "The study indicated that HIF-1α-induced autophagy potentiated epithelial mesenchymal transition (EMT) and migration of pancreatic cancer stem cells, increasing the malignancy of pancreatic cancer." (PMID 32587480, 2020). "In human pancreatic cancer cells, LDHA is upregulated by hypoxia and is directly activated by HIF1‐α." (PMID 32558023, 2020). "We examined the role of HIF-1α, CXCR4, and SDF-1 protein in c-Myc regulation in pancreatic cancer cells." (PMID 32362830, 2020). "The expression of miR-142 is also significantly reduced in patients with pancreatic cancer, and this inhibits the expression of HIF1A and PARK7, which enhances the sensitivity of the pancreatic cancer cells to adriamycin." (PMID 32357493, 2020). "STK33 participated in tumor angiogenesis promoted by HSP90 chaperone via upregulating HIF-1α accumulation and its target gene VEGF secretion in pancreatic cancer." (PMID 32587480, 2020). "In pancreatic cancer, PKM2 upregulated HIF-1α in a NF-κB/p65-dependent manner, inducing VEGF-A expression which contributed to tumor angiogenesis and growth." (PMID 32587480, 2020). "HIF-1α bound to the HRE of STIM1 and elevated its expression, thereby increasing the proliferation of pancreatic cancer cells." (PMID 32587480, 2020).
pancreatic cancer (continued). "Human pancreatic cancer AsPC-1, BxPC-3, and PANC-1 cells showed detectable HIF-1α protein levels during normoxia, as evidenced by western blotting." (PMID 32826949, 2020). "More, in pancreatic cancer, miRNA-646 and LncRNA-MTA2TR are also involved in the regulation of HIF-1α stability, respectively, thereby affecting HIF-1α accumulation in cancer cells." (PMID 33109235, 2020). "HIF-1α and NRP-1 protein levels were both increased after VEGF-A165 stimulation and NRP-1 silencing by shRNA reduced glycolysis in pancreatic cancer cells." (PMID 32085654, 2020). "Currently, promoting the degradation of HIF-1α protein and targeting certain molecules in the HIF-1α signaling pathways are effective therapeutics for pancreatic cancer." (PMID 32587480, 2020). "Clathrin heavy chain (CHC) interacted with HIF-1α and co-localized to the HRE in the VEGF-A promoter region, upregulating VEGF-A expression to increase angiogenesis in pancreatic cancer." (PMID 32587480, 2020). "In pancreatic cancer, HSP90 promoted VEGF-mediated angiogenesis via activating IL-6/HIF-1α/STAT3 autocrine loop." (PMID 32587480, 2020). "HIF-1α-mediated autophagy promoted EMT and metastatic ability of CD133+ pancreatic cancer stem-like cells during intermittent hypoxia." (PMID 33425768, 2020). "Therefore, targeting HIF-1α could be an effective strategy for the treatment of pancreatic cancer." (PMID 32111094, 2020). "Down-regulated miR-142 increased the expression of HIF-1α, upregulating EMT-related proteins, enhancing the invasion and migration of pancreatic cancer cells." (PMID 32587480, 2020). "The expression level of HIF-1α, VEGF, and glucose transporter protein 1 was found to be increased significantly using the immunohistochemical technique in 58 patients with pancreatic cancer and 20 normal human tissue samples." (PMID 31711497, 2019). "Mechanistically, HMGB1 binding with TLR2 receptor functions in a paracrine manner to affect CD133− pancreatic cancer cells dedifferentiation via activating Hippo-YAP pathway and HIF-1α expression in oxygen independent manner in vitro and in vivo." (PMID 31558702, 2019). "The G protein-coupled receptor 55 (GPR55) activates both PI3K/AKT and the MEK/ERK1/2 axis, and promotes the nuclear translocation of HIF-1α and β-catenin, two inducers of Pgp and BCRP in pancreatic cancer cells." (PMID 31117237, 2019). "In pancreatic cancer cells, RAD51 positively regulated cell proliferation, decreased intracellular reactive oxygen species (ROS) production and increased the HIF1α protein level." (PMID 31889908, 2019). "Signaling pathways, such as Notch, tumor necrosis factor alpha (TNFα), transforming growth factor beta (TGF-β), and hypoxia-inducible factor-1 alpha (HIF1α), are involved in the induction of EMT in pancreatic cancer cells." (PMID 31514451, 2019). "To confirm that high glucose-inducedHIF-1α influences the invasive and migratory abilities of pancreatic cancer cells, we used HIF-1α siRNA to knock down HIF-1α." (PMID 30455857, 2018). "Pursuant to the modulation of hypoxia-induced HIF-1α expression, VEGF-A secretion from pancreatic cancer cell lines was significantly reduced upon RICTOR inhibition after incubation with DFX." (PMID 28445935, 2017). "In this study, we investigated the roles of HIF-1α and HIF-2α in TRAIL-induced human pancreatic cancer cell death." (PMID 28476028, 2017). "Hypoxia can induce pancreatic cancer cells to undergo epithelial-to-mesenchymal transition (EMT) via several mechanisms, in which hypoxia-inducible factor 1α (hif-1α) always plays a pivotal role." (PMID 28705232, 2017). "Thus, even though triptolide decreased hypoxia, it also affected the general metabolic pathways in the pancreatic cancer cells leading to decreased IDH1 activity, leading to a decreased synthesis of αKG, which in turn decreased PHD enzyme activity causing an accumulation of HIF-1α in the cells." (PMID 28801636, 2017).
pancreatic cancer (continued). "We investigated the roles of HIF-1α and HIF-2α in cancer cell death induced by tumor necrosis factor (TNF)-related apoptosis-inducing ligand (TRAIL) using human pancreatic cancer cell lines." (PMID 28476028, 2017). "It is important to note that the binding of HIF1-α to the HRE BNIP3 promoter region is inhibited by methylation, thus affecting the expression of BNIP3 in pancreatic cancer cells." (PMID 28968982, 2017). "Incubation with TEPP-46 or BAY 87-2243 resulted in impaired transcriptional activity of both HIF-1α and VEGF-A in hypoxic pancreatic cancer cells." (PMID 26739387, 2016). "Lastly, abrogation of PKM2 prevented hypoxia-mediated HIF-1α accumulation and HIF-1α promoter activity, which negatively impacted VEGF secretion by pancreatic cancer cells deprived of oxygen." (PMID 26739387, 2016). "We showed the possibility that CD133 affects HIF-1α expression, migration and EMT phenomenon in pancreatic cancer." (PMID 27367674, 2016). "Our study suggests that in hypoxic pancreatic tumors PKM2 interferes both with NF-κB/p65 and HIF-1α activation that ultimately triggers VEGF-A secretion and subsequent blood vessel formation." (PMID 26739387, 2016). "The higher uptake subpopulation of cells expressed a high level of HIF-1α and two cancer stem cell-related proteins, CD133 and Oct-4, indicating a better targeting ability of the D-Fe3O4@PMn for pancreatic cancer stem cells." (PMID 27976736, 2016). "In pancreatic cancer cells, PKM2 appears to regulate hypoxia-induced transcriptional activity of both HIF-1α and NF-κB culminating in VEGF transcription and secretion." (PMID 26739387, 2016). "Examination of HIF1α and VEGF expression, however, indicated that oxygen nanobubbles could produce a statistically significant reduction to a level that has been associated with improved treatment outcomes in previous studies using the same pancreatic tumour model." (PMID 28036332, 2016). "In our experimental setup using pancreatic tumor cells, abrogation of PKM2 negatively impacted hypoxia-induced accumulation of HIF-1α." (PMID 26739387, 2016). "In this study, we found that increased DUOX2 expression was associated with a significant increase in the expression of the pro-angiogenic proteins, HIF-1α and VEGF-A, in human pancreatic cancer cells." (PMID 27637085, 2016). "In a human pancreatic cancer cell line, we found that the downregulation of CD133 expression resulted in a decrease in HIF-1α expression, suggesting that CD133 has some role in influencing HIF-1α expression." (PMID 27367674, 2016). "Knock-down experiments indicated that PAK1 is required for proliferation and survival of human pancreatic cancer cell lines through AKT- and/or HIF1α-dependent pathway(s)." (PMID 26774265, 2016). "Graviola treatment also affected the expression of molecules related to hypoxia and glycolysis (HIF-1α, NF-κB, GLUT1, GLUT4, hexokinase II and lactate dehydrogenase-A) in pancreatic cancer cells." (PMID 26979487, 2016). "The fact that VEGF is directly regulated by HIF-1α, an oxygen sensor protein reported to interact with PKM2 urged us to evaluate the role of PKM2 with respect to HIF-1α stabilization and VEGF secretion in hypoxic pancreatic tumors." (PMID 26739387, 2016). "The results revealed that two pancreatic cancer cell lines, PANC-1 and BxPC-3, expressed little HIF-1α and SCF protein under normoxia, and their expressions were obviously increased after hypoxia treatment, especially at 12 hrs." (PMID 25799412, 2015). "In summary, these data demonstrate that in the presence of HIF-1α inhibitor PX-478, GEM gains its ICD-inducing potential on triggering the exposure and release of ICD markers in pancreatic cancer cells." (PMID 25544770, 2015).